WWC1 (WW and C2 domain containing 1)
Description:
Regulator of the Hippo signaling pathway, also known as the Salvador-Warts-Hippo (SWH) pathway. Enhances phosphorylation of LATS1 and YAP1 and negatively regulates cell proliferation and organ growth due to a suppression of the transcriptional activity of YAP1, the major effector of the Hippo pathway. Along with NF2 can synergistically induce the phosphorylation of LATS1 and LATS2 and function in the regulation of Hippo signaling pathway. Acts as a transcriptional coactivator of ESR1 which plays an essential role in DYNLL1-mediated ESR1 transactivation. Regulates collagen-stimulated activation of the ERK/MAPK cascade. Modulates directional migration of podocytes. Plays a role in cognition and memory performance. Plays an important role in regulating AMPA-selective glutamate receptors (AMPARs) trafficking underlying synaptic plasticity and learning (By similarity).
Synonyms: KIBRA; KIAA0869; PPP1R168; HBEBP3; HBEBP36; MEMRYQTL
Tractability: Small molecule: a structure with a bound ligand is known; it has a binding pocket of medium quality. Antibody: its Gene Ontology location is reachable by antibodies, with medium confidence. PROTAC: ubiquitination databases record sites on it; its protein half-life has been measured.
Gene: Protein-coding gene on chromosome 5 (168,291,563 to 168,472,303, forward strand). Ensembl gene ENSG00000113645.
Subcellular location: Cytoplasm, perinuclear region; Nucleus; Cell projection, ruffle membrane; Cytoplasm, cytosol
Subcellular location (Human Protein Atlas): Golgi apparatus
Pathways (Reactome):
Signal Transduction: NOTCH3 Intracellular Domain Regulates Transcription; Signaling by Hippo
Gene Ontology:
Molecular function: kinase binding; molecular adaptor activity; protein binding; signaling adaptor activity; transcription coactivator activity
Biological process: cell migration; hippo signaling; negative regulation of cell population proliferation; negative regulation of hippo signaling; negative regulation of organ growth; negative regulation of transcription by RNA polymerase II; positive regulation of MAPK cascade; regulation of hippo signaling; establishment of cell polarity; regulation of DNA-templated transcription; positive regulation of DNA-templated transcription
Cellular component: cytoplasm; cytosol; nucleus; perinuclear region of cytoplasm; ruffle membrane
Genetic constraint (gnomAD): Loss-of-function variants: 55 observed, 134.69 expected, observed/expected ratio (o/e) 0.41, 90% interval 0.33 to 0.51. The upper end of that interval is the gene's LOEUF score, 0.51, which puts it in group 2 of 6, group 1 being the genes least tolerant of losing a copy. Missense variants: 1,171 observed, 1,397.4 expected, observed/expected ratio (o/e) 0.84, 90% interval 0.8 to 0.88. Synonymous variants: 500 observed, 551.76 expected, observed/expected ratio (o/e) 0.91, 90% interval 0.84 to 0.98.
Homologues: Orthologues: chimpanzee WWC1 (99% identical), dog WWC1 (95% identical), pig WWC1 (95% identical), guinea pig WWC1 (93% identical), rabbit WWC1 (93% identical), mouse Wwc1 (92% identical), rat Wwc1 (92% identical), macaque WWC1 (90% identical), tropical clawed frog wwc1 (69% identical), zebrafish wwc1 (57% identical), Drosophila melanogaster kibra (33% identical). Paralogues in human: WWC2 (53% identical), WWC3 (44% identical).
Diseases named in the same sentence as WWC1 in open-access papers:
WWC1 is named in the same sentence as 69 diseases in open-access papers, as found by Europe PMC text mining. Sharing a sentence is not in itself a finding about the gene and the disease. The quoted sentences say what the papers report.
breast carcinoma (19 papers, 2012 to 2025). "Knockdown WWC1 expression enhanced the migration and invasion of immortalized breast epithelial cells, and reduced expression of WWC1 in claudin‐low breast cancer was associated with poor prognosis." (PMID 31102318, 2019). "Using our microarray data on gene expression and the Ingenuity Pathway Analysis, we predicted the WWC1‐associated signaling pathways in breast cancer." (PMID 31102318, 2019). "WWC1 (WW and C2 domain containing 1) encodes ERα-interacting protein, which participates in ERα transactivation in breast cancer cells." (PMID 31614463, 2019). "The study confirmed that low WWC1 expression was associated with aggressive breast cancer and poor survival outcomes." (PMID 31102318, 2019). "Compared to those with high expression, patients with low WWC1 had higher risk of breast cancer relapse [hazard ratio (HR) = 2.06, 95% confidence interval (CI): 1.26–3.37] and higher risk of death (HR = 2.76, 95% CI: 1.51–5.03)." (PMID 31102318, 2019). "In summary, we found that low WWC1 expression was associated with shorter RFS of breast cancer patients compared to high expression and that the association was independent from tumor grade, disease stage, and hormone receptor status." (PMID 31102318, 2019). "Associations of WWC1 expression with breast cancer survival were analyzed using the Cox proportional hazards regression model and Kaplan–Meier survival analysis." (PMID 31102318, 2019). "In addition, they also found low WWC1 expression was associated with poor outcomes in primary breast cancer." (PMID 33996611, 2021). "Associations of WWC1 expression with breast cancer survival." (PMID 31102318, 2019). "Associations of WWC1 expression with clinical and pathological factors of breast cancer." (PMID 31102318, 2019). "A previous study has demonstrated that breast cancer patients with low expression WWC1 genes usually have larger tumor sizes and poor prognoses." (PMID 36158126, 2022). "Despite growing evidence that WWC1 is involved in breast cancer progression, few studies have evaluated the relationship between tumor characteristics and patient survival." (PMID 34441043, 2021). "A previous study also found that WWC1 formed a complex with dynein light chain 1, an estrogen receptor‐α (ER)‐interacting protein, and played a role in ER transactivation in breast cancer cells." (PMID 31102318, 2019). "Further investigating the biological actions of WWC1 in breast cancer will help to elucidate the mechanisms of tumor progression." (PMID 31102318, 2019). "In this study, 470 breast cancer patients were recruited and WWC1 expression in the tumor samples was measured with quantitative reverse transcriptase PCR." (PMID 31102318, 2019). "To explore the WWC1‐related signaling pathways, we performed co‐expression analysis on genes significantly correlated with WWC1 expression in our breast cancer microarray data." (PMID 31102318, 2019). "Most of the publications in this field link WWC1 function to human breast cancer (BC)." (PMID 33467643, 2021). "The role of YAP in breast cancer and M CSCs is also supported by the studies of YAP/TAZ upstream modulators, Kibra (WW domain-containing protein 1, WWC1) and SREBP (Sterol regulatory element-binding protein)/mevalonate." (PMID 31394796, 2019). "The EZH2-H3K27me3-DNMT1 complex orchestrated epigenetic silencing of the wwc1 gene, a Hippo/YAP pathway upstream effector, in breast cancer epithelial cells." (PMID 31271097, 2019). "E2­activated HSF1 was transcriptionally potent and several genes essential for breast cancer cells growth and/or ERα action, including HSPB8, LHX4, PRKCE, WWC1, and GREB1, were activated by E2 in a HSF1-dependent manner." (PMID 31614463, 2019). "Despite the growing evidence on WWC1's involvement in breast cancer progression, no study has evaluated its relationship with tumor characteristics and patient survival." (PMID 31102318, 2019).
Alzheimer disease (8 papers, 2016 to 2023). A progressive, neurodegenerative disease characterized by loss of function and death of nerve cells in several areas of the brain leading to loss of cognitive function such as memory and language. "WWC1 regulates episodic learning and memory, and genetic nucleotide polymorphism of WWC1 is associated with neurodegenerative diseases such as Alzheimer's disease." (PMID 37528078, 2023). "Other GWASs have implicated SNPs in WWC1 as associated with memory performance and cognition, as well as Alzheimer’s disease." (PMID 28056976, 2017).
gastric cancer (6 papers, 2016 to 2023). A primary or metastatic malignant neoplasm involving the stomach. "Epigenetic regulation of WWC1 expression was also observed in gastric cancer (GC)." (PMID 33467643, 2021).
osteosarcoma (6 papers, 2016 to 2021). A usually aggressive malignant bone-forming mesenchymal neoplasm, predominantly affecting adolescents and young adults. "Decreased WWC1 was shown to maintain the stemness of osteosarcoma cells." (PMID 31102318, 2019). "Specifically, through gene expression analysis of Sox2-regulated genes, it was found that several Hippo pathway-related genes, including Nf2 (Merlin), WWC1 (KIBRA), and YAP, are deregulated in osteosarcomas." (PMID 27240404, 2016). "In osteosarcoma, the transcription factor SRY-Box Transcription Factor 2 (Sox2) was shown to counteract the Hippo pathway and to restrain its two activating components, WWC1 and neurofibromin 2 (NF2, merlin in Drosophila)." (PMID 33467643, 2021). "Due to this inhibitory effect on WWC1 and NF2 transcription, enhanced YAP activity induces the expression of target genes that are important to maintain the cancer stem cell characteristics and differentiation in osteosarcoma." (PMID 33467643, 2021). "Of note, while SOX2 is supposed to bind the 3′ untranslated portion of WWC1 mRNA in osteosarcoma, multiple SOX2 binding peaks are identified in the upper region of WWC1 in ESCC TT cells, suggesting SOX2 can regulate the Hippo‐YAP1 signaling in a context‐dependent manner." (PMID 31560173, 2019).
chronic lymphocytic leukemia (5 papers, 2016 to 2021). "Notably, WWC1 hypermethylation occurs in 70% of B-cell acute lymphocytic leukemias and its epigenetic silencing is also associated with unfavorable prognostic parameters in chronic lymphocytic leukemia." (PMID 28056976, 2017). "Epigenetic control of WWC1 expression also occurred in chronic lymphocytic leukemia (CLL), which is defined as a lymphoma with B cell accumulation in blood, bone marrow and lymph nodes." (PMID 33467643, 2021).
prostate carcinoma (4 papers, 2017 to 2021). A carcinoma that arises from epithelial cells of the prostate gland. "Among these, “WWC1” is known to be associated with prostate cancer." (PMID 28148240, 2017). "The expression of “WWC1” is influenced by AR signaling and is increased in prostate cancer." (PMID 28148240, 2017). "A recent study reported that WWC1 could enhance cell proliferation, migration, and invasion in both immortalized and cancerous prostate epithelial cells, and overexpression of WWC1 was observed in prostate cancer." (PMID 31102318, 2019).
breast tumor (3 papers, 2018 to 2019). "In this study, we found that WWC1 expression was low in breast tumors compared to normal tissues and that low expression was associated with aggressive tumors and poor RFS." (PMID 31102318, 2019). "In a TCGA dataset, WWC1 expression was lower in breast tumors compared to matched adjacent normal tissues (P = 0.043)." (PMID 31102318, 2019).
head and neck squamous cell carcinoma (3 papers, 2019 to 2023). A squamous cell carcinoma that arises from any of the following anatomic sites: lip and oral cavity, nasal cavity, paranasal sinuses, pharynx, larynx, and salivary glands. "ΔNp63α may interact with actin-like protein 6A (ACTL6A), which is a subunit of SWI/SNF CRC and co-amplified with ΔNp63α in head and neck squamous cell carcinoma (HNSCC); this collaboration leads to a downregulation of tumour suppressors such as WWC1 and GPRC5A." (PMID 36760085, 2023).
melanoma (3 papers, 2024 to 2025). A malignant, usually aggressive tumor composed of atypical, neoplastic melanocytes. "Risk forest plot analysis revealed that SFN, PLA2G4E, SERPINB5, WWC1, PAK6, and TEAD3 were the most influential genes in promoting melanoma malignancy." (PMID 41034991, 2025). "We also found that although some established YAP/TAZ target genes (CRIM1, F3, ANKRD1) correlated strongly with CTGF and CYR61 expression in human melanoma, others did not (WWC1, FOSL1, FSTL3)." (PMID 38473214, 2024).
acute kidney injury (2 papers, 2022 to 2023). Sudden and sustained deterioration of the kidney function characterized by decreased glomerular filtration rate, increased serum creatinine or oliguria. "lncRNA XIST targets miR-155-5p and upregulates WWC1 to dampen inflammatory cytokine generation and cell apoptosis, hence attenuating acute kidney injury induced by sepsis." (PMID 36333771, 2022).
acute lymphoblastic leukemia (2 papers, 2018 to 2021). Leukemia with an acute onset, characterized by the presence of lymphoblasts in the bone marrow and the peripheral blood. "Epigenetic regulation of WWC1 expression was shown to correlate with progression of acute lymphocytic leukemia (ALL)." (PMID 33467643, 2021).
colorectal cancer (2 papers, 2018 to 2022). A primary or metastatic malignant neoplasm that affects the colon or rectum. "WWC1 was low expressed in colorectal cancer tissues, and low-level WWC1 indicated worse survival of colorectal cancer patients." (PMID 36158126, 2022).
esophageal squamous cell carcinoma (2 papers, 2019 to 2022). Esophageal squamous cell carcinoma (ESCC) is a type of esophageal carcinoma (EC) that can affect any part of the esophagus, but is usually located in the upper or middle third. "A previous study revealed that WWC1 overexpression hindered the SOX2-induced migration ability and invasive potential in esophageal squamous cell carcinoma." (PMID 36158126, 2022).
Hypertension (2 papers, 2017 to 2020). The presence of chronic increased pressure in the systemic arterial system. "Another study reported that the T allele of rs17070145 of WW and C2 domain containing one (WWC1 or KIBRA) gene was associated with lower executive function, especially in women with hypertension." (PMID 33352859, 2020).
intrahepatic cholangiocarcinoma (2 papers, 2022 to 2025). A carcinoma that arises from the intrahepatic bile duct epithelium in any site of the intrahepatic biliary tree. "Another study has revealed that WWC1 cooperated with NF2 to mitigate the malignant progression of intrahepatic cholangiocarcinoma by activation of LATS1/2 and inhibition of YAP/TAZ activity." (PMID 36158126, 2022).
Tourette syndrome (2 papers, 2017 to 2023). A neurologic disorder caused by defective metabolism of the neurotransmitters in the brain. "Variants in DIP2C (disco interacting protein 2 homolog C) and DNAH17 (dynein axonemal heavy chain 17) have been previously linked to ASD, and WWC1 was identified as a risk gene for Tourette syndrome, another NDD known to be comorbid with ASD." (PMID 37686052, 2023).
glomerular disease (1 paper, 2023). "Here, we tested the consequences of transgenic podocyte-specific WWC1 expression in immortalized human podocytes and in mice, and we explored the association between glomerular WWC1 expression and glomerular disease progression." (PMID 36853804, 2023). "Glomerular WWC1 expression is associated with glomerular disease progression." (PMID 36853804, 2023). "Of clinical relevance, glomerular WWC1 expression negatively correlated with renal survival among patients with primary glomerular diseases." (PMID 36853804, 2023). "We also show that increased WWC1 glomerular expression correlates with decreased renal survival in biopsy-proven glomerular disease." (PMID 36853804, 2023). "Increased glomerular WWC1 expression levels were significantly associated with reduced renal survival, suggesting the prognostic importance of WWC1 upregulation to the progression of glomerular disease." (PMID 36853804, 2023). "However, due to limited patient sample size and low event rate of the composite renal endpoint, we were not able to assess differences between WWC1 expression and disease outcomes based on glomerular disease subtype, though this is an important consideration for future analyses." (PMID 36853804, 2023).
lung adenocarcinoma (1 paper, 2022). A carcinoma that arises from the lung and is characterized by the presence of malignant glandular epithelial cells. "It was reported that WWC1 was downregulated in lung adenocarcinoma tissues and cells, and WWC1 restrained proliferation and invasion and accelerated apoptosis of lung adenocarcinoma cells by Hippo signaling pathway." (PMID 36158126, 2022).
Nephropathy (1 paper, 2023). A nonspecific term referring to disease or damage of the kidneys. "Here we tested the association between glomerular WWC1 expression and longitudinal kidney disease outcomes." (PMID 36853804, 2023).
thyroid cancer (1 paper, 2022). "Dual-luciferase detection showed that WWC1, SAV1 and LAST2 were direct targets of miR-424-5p in thyroid cancer cells and were negatively correlated." (PMID 35409396, 2022). "Therefore, miR-424-5p suppresses the activity of Hippo signal transduction by targeting WWC1, SAV1 and LAST2, thus promoting lung metastasis and the anoikis resistance of thyroid cancer." (PMID 35409396, 2022).